UBE4B (ubiquitination factor E4B)
Diseases named in the same sentence as UBE4B in open-access papers (continued):
Sharing a sentence is not in itself a finding about the gene and the disease.
neurodegenerative disease (2 papers, 2012 to 2019). A disorder of the central nervous system characterized by gradual and progressive loss of neural tissue and neurologic function. "Normally, UBE4B is a factor regulating the development of the nervous system and can be a target molecule in neurodegenerative disease treatments." (PMID 31878315, 2019). "Based on that finding, Ube4b is considered to be a rate-limiting factor in mediating the ubiquitination and polygutamine aggregation in neurodegenerative diseases." (PMID 23222733, 2012). "Therefore, regulatory molecules that affect protein expression and activity, such as UBE4B, will be a turning point in the field of neuronal physiology and neurodegenerative disease." (PMID 23222733, 2012). "Many of the hypotheses presented here are gateways to understanding the programmed death/survival of neurons regulated by UBE4B in normal physiology, and a means of introducing potential therapeutic approaches with implications in treating several neurodegenerative diseases." (PMID 23222733, 2012).
UBE4B also shares sentences with these, for which no sentence is quoted: cardiomyopathy (1 paper); cardiovascular diseases (1); cholangiocarcinoma (1); colorectal (1); dermatosparaxis (1); diabetes (1); endometrial carcinoma (1); epilepsy (1); Esophageal Carcinoma (1); frontotemporal dementia (1); ganglioneuroblastoma (1); head and neck squamous cell carcinoma (1); Kidney Chromophobe (1); left ventricular noncompaction (1); liver cancer (1); Lung Squamous Cell Carcinoma (1); mastitis (1); melanoma (1); metastatic disease (1); Obesity (1); oral squamous cell carcinoma (1); Paget's disease of bone (1); sarcoma (1); serous ovarian cancer (1); Stroke (1); tauopathy (1); Thyroid Carcinoma (1).